BCL2 (BCL2 apoptosis regulator)
Diseases named in the same sentence as BCL2 in open-access papers (continued):
Sharing a sentence is not in itself a finding about the gene and the disease.
tumor (continued). "Eventually, the tumor growthin the experimental group (Bcl-2-SNA) was almost completely inhibited,and the tumor inhibition rate was as high as 95%, which proved the huge prospectsfor cancer treatment by controlling cell apoptosis." (PMID 37101570, 2022). "The Bcl2 protein binds to proapoptotic members, such as BAX, a protein that induces cell death in tumor cells, to prevent pore formation and cytochrome c release." (PMID 35070357, 2022). "By using in vitro and in vivo models of primary and secondary ibrutinib resistance as well as post‐ibrutinib treatment clinical samples, we show that dual targeting of the BCL‐2 and PI3‐kinase signalling pathways results in synergistic anti‐tumour activity." (PMID 35352453, 2022). "Tumor cells were positive with regard to the membranous and cytoplasmic expression of CD34, bcl-2, and CD99 and furthermore showed nuclear STAT6 positivity (respectively)." (PMID 36428694, 2022). "In the tumor tissues of AGK knockdown group, we found that the expression of BCL-2 was upregulated, but the phosphorylation of FOXO1 and AKT was significantly decreased." (PMID 35910796, 2022). "Immunohistochemical staining for BCL-2, BAX and caspase-3 in tumour sections exhibited a marked decrease in BCL-2, Ki67 and pAKT and an increase in BAX and caspase-3 activity and expression in the tumours generated with ALKBH5- cells." (PMID 35414790, 2022). "In this study, expression levels of BAX, Caspase-3, Caspase-9, and cleaved Caspase-3 in the blood and tumor tissues of BGC-823-bearing nude mice were increased, while Bcl-2 expression was relatively low." (PMID 36438804, 2022). "For example, the miR-125 as a tumor suppressor reduces the antiapoptotic effect of the MUC1 and Bcl-2 genes and suppresses vascular endothelial growth factor (VEGF) expression, thereby inhibiting tumor proliferation and metastasis formation." (PMID 35326471, 2022). "In order to phenocopy increased apoptotic priming that is found in pre-malignant and tumor cells, we co-treated cells with ABT-737, a BH3-mimetic compound that selectively neutralizes anti-apoptotic BCL-2, BCL-xL, and BCL-w." (PMID 35447090, 2022). "Investigations demonstrate that a combination of PLK1 (BI2536) and Bcl-2 (ABT199) inhibitors synergized and induced apoptosis in FBXW7 low, and c-MYC overexpressing, tumor cells." (PMID 35346215, 2022). "The immunohistochemical image showed less Bcl-2 expression and more TNFRSF9 expression in the pLV-TNFRSF9 injected tumor." (PMID 35799609, 2022). "We have previously revealed that miR-204 was capable of down-regulating multiple targets, such as BCL2 and RAB22A, in tumor cells." (PMID 36231028, 2022). "Immunohistochemical analysis of tumor tissues showed that p-STAT3, Bcl-2, and survivin were changed accordingly." (PMID 35710492, 2022). "Deletion of IL30 dramatically downregulated BCL2, NFKB1, STAT3, IGF1 and CXCL5, whereas tumor suppressors, primarily SOCS3, were upregulated." (PMID 36224639, 2022). "Protein and mRNA expression of Bax, Bcl-2, p-PI3K, p-Akt, p-MAPK, p-ERK, and p-CREB in tumor tissues were detected." (PMID 36254198, 2022). "MiR-148a, in addition to PD-L1, inhibits the human epidermal growth factor receptor 3 (HER3), Wnt/β-catenin pathway ligand—WNT10b, apoptosis regulator—BCL2, as well as VEGF and HIF1 in CRC; that is, it acts as a tumor suppressor." (PMID 36012588, 2022). "We have also tested the mRNA expression of apoptosis-relevant genes (BAX, BCL-2 and CASP3) in tumor tissues of our model mice, and a TUNEL assay in tissue slices, which revealed an elevated apoptosis tendency in FBXO17-overexpressed mice implanted tumor." (PMID 36035375, 2022). "In view of this situation, if BCL-2 and BCL-XL can be functionally blocked, the apoptosis of tumor cells can be restored." (PMID 36313628, 2022).
tumor (continued). "CAF-secreted midkine enhances tumor cell resistance to cisplatin by inducing ANRIL expression and increasing anti-apoptotic protein Bcl-2 expression." (PMID 35978835, 2022). "Four tumor apoptosis-related proteins and genes, Cleaved Caspases, BAX, Bcl-2, and VEGF, were detected by immunohistochemical staining, western blotting, and RT-PCR." (PMID 35597811, 2022). "Some researchers have suggested that CXCR4-overexpressing cells downregulate the expression of cyclin D1 and Bcl-2 and activate other signaling pathways such as MAPK to support cell proliferation and tumor progression." (PMID 35941537, 2022). "Meanwhile, treatment with BDMC up-regulated the expressions of BAX and cleaved caspase-3, while it down-regulated the protein expressions of Bcl-2 and XIAP in the tumor tissues compared with the control group." (PMID 35008959, 2022). "AML patients with higher risk scores were predicted to exert a worse sensitivity against anti-tumor agents including Midostaurin (an FLT3 inhibitor), ABT-263 (a BCL-2 inhibitor), Bleomycin, Bosutinib, and Lenalidomide." (PMID 34784264, 2022). "β-Carotene, at the normal achievable level of just 1 μM, efficiently decreased the activity of anti-apoptotic molecules such as Bcl-2 and PARP, as well as nuclear factor NF-κB, in human tumour MCF-7 cells." (PMID 35276890, 2022). "Activation of ERK can promote the phosphorylation of Bcl-2, inhibit the apoptosis of HCC cells, and promote tumor development." (PMID 35308206, 2022). "Further, tumor and normal tissues of CRC-82 were analyzed for RNA expression of BCL2, BCL-XL, and BCL-W by RT-PCR." (PMID 36430867, 2022). "miR-185-5p targets ROCK2, ELK1, ELK3, IGF2, RAGE, BCL2, BCL2L1, and many other genes to suppress tumor cell migration and invasion." (PMID 35223832, 2022). "Significant inhibition in tumour size, microvessel density, and expressions of Bcl-2 and CDK6 was observed in mice bearing tumours." (PMID 35457210, 2022). "It significantly developed health parameters by improving Caspase 3, Bax, Bcl2, iNOS and SOD genes in the tumor tissue." (PMID 36552412, 2022). "We observed that only a high dose of SCT (10 mm) induced increases of cleaved caspase‐3 and Bax expression, as well as decreases of Bcl‐2/Bax ratio and Mcl‐1 in both HCT116 and HT1299 tumor cells." (PMID 34747157, 2022). "An example of replacement therapy is the restoration of miR-34a expression in various types of cancer (e.g., lung, colon, pancreas), which led to inhibition of tumor development and inducing programmed cell death by regulating Notch 1, HMGA2 or Bcl-2." (PMID 35269947, 2022). "ABCB1, BAX, BCL2, FADD, FAS, and several tumour protein families were identified as the genes responsible for such findings." (PMID 35884999, 2022). "On the cellular level, the PIP-NMs/MTX-MNMs formula enhanced the regression of tumor via downregulation of TGF-β and Bcl-2, as confirmed by histological and immunohistochemical analysis." (PMID 36559161, 2022). "To investigate the mechanism behind CI-induced cell cycle arrest and apoptosis, we employed PPI (protein–protein interaction) to identify the top 10 genes related to tumor, cell cycle, and apoptosis, including CDK1 and Bcl2." (PMID 35450041, 2022). "Through immunohistochemical staining, it was showed that in tumor tissues, the increase of BNIP3 promoted the expression of Ki67 and Bcl-2 protein, and inhibited Bax protein." (PMID 35783530, 2022).
tumor (continued). "The results showed that phenolic rich fractions improved health condition of mice by improving Caspase 3, Bax, Bcl2, iNOS and SOD genes in the tumor tissue." (PMID 36552412, 2022). "The weakening of apoptosis often leads to tumorigenesis, and the overexpression of antiapoptotic oncogenes such as BCL-2/BCL-XL, MCL1 or the IAP proteins is conducive to the survival of tumor cells." (PMID 36713522, 2022). "At present, preclinical experiments have proved that ixazomib has not only anti-tumor activity in DLBCL cell lines, but also inhibitory activity in DLBCL cell lines that have translocation of MYC and BCL2, and its IC50 value is 40-200 nm." (PMID 35303910, 2022). "Researchers showed that the overexpressed Bcl-2 in tumors seriously abrogated the killing effects of CD8+ CTLs and NK cells on tumor cells." (PMID 36080223, 2022). "Venetoclax is a small molecule of pyrrolopyridine that mimics native ligands of BCL-2, and binds to it with high selectivity, thereby repressing BCL-2 activity and restoring tumor apoptotic processes." (PMID 36358759, 2022). "The data demonstrated that TAX promoted the expression of the pro-apoptotic gene Bax, Caspase-3, and Caspase-9, and inhibited the expression of the anti-apoptotic gene Bcl-2 and oncogene Poly ADP ribose polymerase (PARP1) in SPC-A1 and LLC tumor cells." (PMID 36230568, 2022). "Metabolic plasticity is a complex process involving multiple oncogenes (e.g. BCL2) and phenotypic shifts like EMT, as well as cross-talk with the tumor microenvironment." (PMID 35365706, 2022). "Short interfering RNA (siRNA) with 5'ppp-moeity has been used to silence Bcl-2 and activate RIG-I leading to apoptosis of tumour cells in a murine model of lung metastases." (PMID 35998812, 2022). "Researchers found that Huaier can decrease the expressions of Bcl-2, MMP-2, and MMP-9 in the MKN-45 cell line, thus inducing apoptosis and preventing the invasion of tumor cells." (PMID 35991644, 2022). "In human DLBCL tumor tissues, the expression of AGK inversely correlated with BCL-2 expression, as well as the amounts of nuclear FOXO1." (PMID 35910796, 2022). "Further, it was found that miR766-3p supports cancer cell survival and metastasis by affecting Bax/Bcl-2 and EMT pathways leading to aggressive tumor behavior." (PMID 36358691, 2022). "Injection of miR-16 mimetics led to a decrease in Bcl-2 and CCND1 expression levels and also inhibited tumor growth in animal models of malignant pleural mesothelioma." (PMID 36012588, 2022). "It has been demonstrated that these two compounds promoted apoptosis in primary leukemic cells and reduced tumor growth in different mouse models, likely via NF-κB inhibition and, with regard to IBET-151, also partially via BCL-2 inhibition." (PMID 35884618, 2022). "The results showed that the expression of drug resistance proteins MRP1 and P-gp, anti-apoptotic proteins Bcl-2, and Bcl-xL decreased after treatment with DHTS in HCT116/OXA cells and tumor tissues." (PMID 36431875, 2022). "Taken together, we have here demonstrated that silencing of SND1 increases the level of several tumor suppressor miRNAs and sensitizes cancer cells especially to MEK-ERK pathway inhibitors and Bcl-2/Bcl-XL inhibitor navitoclax." (PMID 35804872, 2022).
tumor (continued). "Using quantitative Bcl-2 protein profiles of BAK, BAX, BCL2, BCL(X)L, and MCL1 as model input for DR_MOMP, we were able to calculate the sensitivity of individual tumor cells to the process of mitochondrial apoptosis initiation." (PMID 34754079, 2022). "Meanwhile, the WB results of Bcl-2 and Bax expression proved the conclusion that OE-ZNF268 enhanced the cell apoptosis, which contributing to the anti-tumor performances." (PMID 35735115, 2022). "Interfering with EEF1D gene expression in mice xenografted tumor significantly affected the levels of OPTN, p-Akt, Bcl-2, Bax, cleaved caspase-3 and ERCC1 compared to DDP treated mice alone, and had less effect on PI3K, Akt and caspase-3." (PMID 35672728, 2022). "In the DOX-nano group, the weight of the tumor tissues were significantly lighter, and the expression of multidrug resistance-related proteins, including MRP, LRP, BCRP, Bcl-2, and PKC-α was significantly lower." (PMID 36296934, 2022). "Similarly to oncogene addiction, some tumor cells may be dependent on BCL-2 for survival." (PMID 36142875, 2022). "Consistently with transcriptomic analysis, we also observed marked differences in the mRNA levels of BAX, HRK, CDK6, CDK14, and BCL2 between the sgCONT and NOXAKO tumor cells after co-incubated with CD19 CAR T cells." (PMID 35370290, 2022). "In accordance with the results of apoptotic protein in tumor tissues, FJD treatment increased the levels of Bax, Cyt-C, and cleaved caspase-3 and reduced Bcl-2 in SKOV3 and 3AO cells." (PMID 35281608, 2022). "Immunohistochemical analysis of the tumour tissues showed changes in the protein expression of MMP9, vimentin, Bax, Bcl‐2, p‐p65, CDK9, MMP2, N‐cadherin and MIF." (PMID 35060345, 2022). "Other studies of constitutive expression of Bcl2 in CAR-T cells resulted in prolonged T cell survival and tumor control in murine lymphomas." (PMID 35573704, 2022). "Oral BCL-2 inhibitor venetoclax is one of most promising strategies to treat lymphoproliferative diseases, given the overexpression of BCL-2 protein in tumor cells." (PMID 35328789, 2022). "To delineate the potential of MCL1 to limit the clinical activity of chemotherapy such as doxorubicin or oxaliplatin, we evaluated the expression of MCL1 and the related family members Bcl-2 and Bcl-xL in a large panel of CRC tumor biopsies (n = 133) by IHC." (PMID 35042842, 2022). "The results of Western blotting showed that 200 mg/kg NaBu inhibited the expressions of Bcl‐2 and PCNA in the mouse tumour tissues." (PMID 35429101, 2022). "Western blotting was performed to analyze the expression levels of PI3K, OPTN, Akt, p-Akt, Bcl-2, Bax, caspase-3, cleaved caspase-3, ERCC1 and β-actin in the xenograft tumor tissues of mice." (PMID 35672728, 2022). "Decreased the protein expression of CDK2, CDK4, cyclin E, and Bcl-2 and increased the expression of CDKN1BElevated the ratio of LC3-II/LC3-I.Decreased tumor size and weight." (PMID 34026649, 2021). "The network consists of a system of ordinary differential equations (ODEs) involving eight variables: concentrations of STAT1, STAT3, Bcl-2, BAX, IFN-β, JAK2 and DDP and tumour volume." (PMID 34631119, 2021). "Furthermore, TUNEL staining revealed that the proportion of TUNEL‐positive cells in xenografts of PC‐9‐derived LCSC tumour‐bearing mice was increased after anlotinib treatment in addition to the up‐regulated expression of Bax and cleaved caspase‐3 and the down‐regulated expression of Bcl‐2." (PMID 33955683, 2021). "There was a highly significant increased expression of Bcl-2 in group III as compared to both groups I and II at different durations and on 30 and 40 days from the onset of tumor formation as compared to group IV (P< 0.001)." (PMID 33773560, 2021).
tumor (continued). "Taken together, these results indicated that the Bcl-2 enhanced the anti-tumor activity of CAR-T cells in vivo and prolonged survival of tumor-bearing mice." (PMID 33429845, 2021). "Consistent with the in vitro experiments, in nude mice exnografted with MGC 803 cells, galangin inhibited tumor growth and reversed the abnormally expressed proteins, such as p-JAK2, p-STAT3, Bcl-2, cleaved caspase-3, cleaved PARP, and Ki67." (PMID 33981228, 2021). "More importantly, we confirmed that ICT1 protein levels had a positive correlation with the expression levels of BCL-2 in both xenografted tumor tissues and tissues derived from OS patients and that ICT1 regulated BCL-2 by controlling STAT3 phosphorylation." (PMID 33585660, 2021). "An increase in tumor cell sensitivity to the cytotoxic action of cetuximab in CRC was also observed, through a reduction of BCL2 and an increase in the activity of caspases 3/7." (PMID 34199293, 2021). "We examined the correlation between SOX2, Bax, or Bcl-2 expression with liver function tests (LFT), including AST, ALT, ALP, as well as alpha-fetoprotein (AFP) tumor marker." (PMID 34436030, 2021). "Comparative analysis of BCL-2 gene expression in the PE/CA-PJ49 and FaDu cell lines showed that the two types of tumor cells had a similar response to CisPt treatment as well as to the combined CisPt + RSV treatment." (PMID 34204834, 2021). "Analysis of apoptosis-related genes, including BAX, BCL2, and CASP3, and also BAX/BCL2 ratio indicated CAP induces apoptotic pathway selectivity in tumor cells." (PMID 34825002, 2021). "We also observed increased expression of B7-H3, Bcl-2, CTLA4, LAG3, Tim-3, PD1, PDL1 and STING in the second sample compared with the first sample (and some differences appear contingent upon the tumor or stroma compartment)." (PMID 34838031, 2021). "We describe the clinical presentation of this rare tumour of the sinonasal and oral cavity, including upper airway obstruction, and the importance of immunohistochemical markers such as CD34 and BCL-2 in diagnosing SFT." (PMID 34849218, 2021). "Treatment with CisPt significantly reduced BCL-2 gene expression in FaDu (p < 0.05, *) and PE/CA-PJ49 (p < 0.025, *) tumor cell lines compared to the effect induced on the HaCaT normal line." (PMID 34204834, 2021). "In this study we show another inhibitor, AZD4320 that targets BCL-XL (and BCL-2), can also potently kill MPM tumor cells in vitro (EC50 values in the 200 nM range) and this effect is enhanced by co-inhibition of MCL-1 using AZD5991." (PMID 34050131, 2021). "Consistently, the protein levels of TRIM44, p-STAT3, BCL2, MMP9, HIF-1α and PIM1 were all decreased in SPATS2 knockdown tumor tissues, which underpinned the contribution of SPATS2-TRIM44-p-STAT3 axis to tumorigenic events in HCC." (PMID 33391405, 2021). "A PIAS3-deta peptide can significantly downregulate the expression of the tumor proliferation-related proteins STAT3, pSTAT3, Bcl-2, Cyclin D1, PCNA and c-myc and effectively inhibit the proliferation of HCC cells." (PMID 34976809, 2021). "Ceramide is known to be a tumor suppressor, promoting PP2A phosphatase activity, and leading to dephosphorylation of the anti-apoptotic protein Bcl-2." (PMID 34768523, 2021). "While the intermediate level of TZB treatment attains the maximal ET due to up-regulated Bcl-2 expression and sustained apoptosis activity (the case (ii)), high doses of TZB leads to lower anti-tumor efficacy from the large population of CSCs (the case (iii))." (PMID 34669701, 2021). "miR-29, miR-15a, and miR-16 target and repress the translation of tumor-suppressor and cell cycle proteins, including NOTCH1, BCL2, and cyclin." (PMID 34064804, 2021).